TMBIM6 (transmembrane BAX inhibitor motif containing 6)
Description:
Endoplasmic reticulum (ER)-resident protein that confers cellular protection as an anti-apoptotic protein by limiting multiple stress-inducing pathways surrounding the endoplasmic reticulum and mitochondria. Inhibits the activities of the key sensor for the endoplasmic reticulum unfolded protein response IRE1alpha/ERN1 both directly and by blocking BAX/BAK binding. Modulates ER calcium homeostasis by acting as a calcium-leak channel. Negatively regulates autophagy and autophagosome formation, especially during periods of nutrient deprivation, and reduces cell survival during starvation (By similarity).
Synonyms: BI-1; TEGT; BAXI1
Tractability: Antibody: its Gene Ontology location is reachable by antibodies, with high confidence; UniProt predicts a signal peptide or a membrane-spanning region. PROTAC: UniProt records ubiquitination sites on it; ubiquitination databases record sites on it; its protein half-life has been measured.
Gene: Protein-coding gene on chromosome 12 (49,707,725 to 49,764,935, forward strand). Ensembl gene ENSG00000139644.
Subcellular location: Endoplasmic reticulum membrane
Gene Ontology:
Molecular function: endoribonuclease inhibitor activity; enzyme binding; protein binding; ubiquitin protein ligase binding; calcium channel activity
Biological process: cellular response to unfolded protein; negative regulation of apoptotic process; negative regulation of apoptotic signaling pathway; negative regulation of calcium ion transport into cytosol; negative regulation of endoplasmic reticulum stress-induced intrinsic apoptotic signaling pathway; negative regulation of hypoxia-induced intrinsic apoptotic signaling pathway; negative regulation of IRE1-mediated unfolded protein response; negative regulation of RNA splicing; response to L-glutamate; calcium ion transmembrane transport; negative regulation of immunoglobulin production; negative regulation of transcription by RNA polymerase II; response to endoplasmic reticulum stress
Cellular component: cytoplasm; endoplasmic reticulum; endoplasmic reticulum membrane; membrane; nucleus; plasma membrane
Genetic constraint (gnomAD): Loss-of-function variants: 13 observed, 33.06 expected, observed/expected ratio (o/e) 0.39, 90% interval 0.25 to 0.62. The upper end of that interval is the gene's LOEUF score, 0.62, which puts it in group 2 of 6, group 1 being the genes least tolerant of losing a copy. Missense variants: 275 observed, 304.97 expected, observed/expected ratio (o/e) 0.9, 90% interval 0.82 to 1. Synonymous variants: 85 observed, 108.04 expected, observed/expected ratio (o/e) 0.79, 90% interval 0.66 to 0.94.
Homologues: Orthologues: chimpanzee TMBIM6 (99% identical), guinea pig TMBIM6 (95% identical), macaque TMBIM6 (94% identical), dog TMBIM6 (94% identical), mouse Tmbim6 (94% identical), pig TMBIM6 (94% identical), rabbit TMBIM6 (90% identical), rat Tmbim6 (89% identical), zebrafish tegt (68% identical), tropical clawed frog tmbim6 (65% identical), Drosophila melanogaster BI-1 (37% identical). Paralogues in human: TMBIM4 (27% identical), GHITM (24% identical), FAIM2 (19% identical), TMBIM1 (17% identical), GRINA (16% identical).
Diseases named in the same sentence as TMBIM6 in open-access papers:
TMBIM6 is named in the same sentence as 85 diseases in open-access papers, as found by Europe PMC text mining. Sharing a sentence is not in itself a finding about the gene and the disease. The quoted sentences say what the papers report.
laryngeal squamous cell carcinoma (15 papers, 2021 to 2025). A squamous cell carcinoma that arises from the larynx. "RBM15 has been manifested to mediate m6A modification of transmembrane BAX inhibitor motif containing 6 (TMBIM6) mRNA via depending on the reader protein IGF2BP3 in laryngeal squamous cell carcinoma." (PMID 41272900, 2025). "For example, Overexpression of RBM15 increased laryngeal squamous cell carcinoma cell proliferation, migration, invasion, and apoptosis by regulating TMBIM6 stability in an IGF2BP3-dependent manner." (PMID 38765115, 2024). "In laryngeal carcinoma, RBM15 and IGF2BP3 are involved in m6A methylation modification of TMBIM6, thereby regulating the expression of TMBIM6 in laryngeal squamous cell carcinoma (LSCC)." (PMID 36793593, 2023). "The role of IGF2BP3 modulates laryngeal squamous cell carcinoma progression through TMBIM6 mRNA." (PMID 38355626, 2024). "Growing evidences has indicated that TMBIM6 exert an oncogenic role in multiple cancers, including squamous cervical, non-small cell lung, breast, nasopharyngeal, hepatocellular, glioblastoma, and laryngeal squamous cell carcinoma." (PMID 36639675, 2023). "Moreover, RBM15 has been reported to promote the occurrence and development of laryngeal squamous cell carcinoma by maintaining the stability of TMBIM6." (PMID 36803098, 2023). "The m6A modification of TMBIM6 mediated by RBM15 increases its stability in an IGF2BP3-dependent manner, promoting the development and progression of laryngeal squamous cell carcinoma." (PMID 40435202, 2025). "RBM15 regulates the stability of TMBIM6 in an IGF2BP3-dependent manner, promoting the progression of laryngeal squamous cell carcinoma." (PMID 39039611, 2024). "For instance, in laryngeal squamous cell carcinoma, RBM15 enhances the malignant progression by promoting m6A modification of TMBIM6, thereby increasing TMBIM6 mRNA levels." (PMID 39716068, 2024). "first demonstrated that the m6A writer RBM15 was overexpressed in laryngeal squamous cell carcinoma (LSCC) and facilitated the progression of LSCC by regulating m6A-based TMBIM6 mRNA, and TMBIM6 m6A modification regulated cell apoptosis." (PMID 35090469, 2022). "RBM15-mediated m6A modification of TMBIM6 mRNA enhances the stability of TMBIM6 mRNA in an IGF2BP3-dependent manner and promotes the progression of laryngeal squamous cell carcinoma." (PMID 35945641, 2022). "Third, TMBIM6, as a mediating gene discovered for HNSC, played an important role in the progression of laryngeal squamous cell carcinoma as a downstream target of RBM15-mediated N6-methyladenosine modification." (PMID 34464378, 2021).
breast carcinoma (11 papers, 2011 to 2025). "Several clinical studies have indicated an association between TMBIM6 expression and breast cancer 9-11." (PMID 37057283, 2023). "We next investigated the underlying intracellular signaling mechanism of the TMBIM6 knockdown phenotypes in breast cancer cells." (PMID 37057283, 2023). "The present study revealed that high expression of TMBIM6 in breast cancer is associated with cancer invasiveness." (PMID 37057283, 2023). "The analysis showed that the risk of breast cancer mortality increased with high expression of Sp1 and TMBIM6." (PMID 31336725, 2019). "Supporting this observation, the TCGA dataset analysis showed that the breast cancer patients with high expression levels of Sp1 and TMBIM6 increased the risk of cancer mortality." (PMID 31336725, 2019). "Furthermore, miR‐302d‐3p‐mediated regulation of TMBIM6 has been implicated in breast cancer cell viability, migration, and apoptosis, highlighting the potential therapeutic implications of targeting TMBIM6 and its associated downstream signaling pathways." (PMID 38766879, 2024). "In this study, we investigated whether high expression of TMBIM6 in breast cancer was significantly associated with cancer invasiveness." (PMID 37057283, 2023). "For instance, in breast cancer, TMBIM6 has been shown to modulate cell death pathways and promote cancer invasiveness." (PMID 38766879, 2024). "We show that TMBIM6 was highly expressed in breast cancer samples using mRNA expression assays and the ONCOMINETM database." (PMID 37057283, 2023). "Knockdown of TMBIM6 reduced proliferation and migration of invasive breast cancer cells through downregulation of the MAPK/ERK signaling pathway." (PMID 37057283, 2023). "Overall, our data demonstrated that TMBIM6-induced miR-181a up-regulation plays an important role in the efficient modulation of migration and invasion of breast cancer cells." (PMID 37057283, 2023). "It is possible that the TMBIM6-induced progression and metastasis of breast cancer can be mediated through MMP-2 and/or MMP-9." (PMID 37057283, 2023). "We first examined TMBIM6 expression in breast cancer cell lines, which showed high correlation between TMBIM6 expression and cancer prognosis." (PMID 32782388, 2020). "RNA-seq analysis of breast cancer patient’s samples from the TCGA database inferred the positive correlation between Sp1 and TMBIM6 gene expressions." (PMID 31336725, 2019). "The BAX inhibitor 1 (TMBIM6) acts as oncogene by inhibiting apoptotic cell death and its expression is upregulated in human breast cancer." (PMID 24098698, 2013). "In addition, knockdown and overexpression of TMBIM6 modulated proliferation and migration of invasive breast cancer cells by regulating MAPK/ERK signaling pathway." (PMID 37057283, 2023). "The current study is also a remarkable report describing another new molecular mechanism related to the TMBIM6-induced migration and invasion and has identified the key molecules and signaling pathways involved in the interaction of TMBIM6 and miR-181a in breast cancer cells." (PMID 37057283, 2023). "We therefore propose that TMBIM6-induced miR-181a upregulation could effectively regulate the migration and invasion of breast cancer." (PMID 37057283, 2023). "To investigate the role of TMBIM6 in breast cancer cells, we analyzed TMBIM6 and EMT markers expression in a panel of MCF10A cells as human immortalized normal breast epithelial cells and MCF-7, MDA-MB231, and MDA-MB468 as breast cancer cell lines with varying prognosis." (PMID 37057283, 2023). "Especially, in breast cancer, expression of TMBIM6 was up-regulated compared to in normal tissue." (PMID 37057283, 2023). "Given that TMBIM6 is one of the most important oncogenes in human breast cancer and an attractive therapeutic target, our findings may provide a molecular basis for the role of TMBIM6 in the promotion of breast cancer progression." (PMID 37057283, 2023).
breast carcinoma (continued). "In this study, we propose that TMBIM6-mediated miR-181a leads to migration and proliferation of breast cancer cells through activation of MAPK/ERK, which may affect malignant progression." (PMID 37057283, 2023). "Moreover, we found that TMBIM6 was up-regulated in bladder, lung, lymphoma, colorectal, and breast cancers, but specially increased in ductal or invasive breast carcinoma compared to in their normal tissue 41-50." (PMID 37057283, 2023). "However, further investigation is still required to elucidate the role of ERK activation in the TMBIM6-mediated mammary tumor progression." (PMID 37057283, 2023). "Furthermore, RNA-seq data analysis from TCGA data showed a positive correlation between TMBIM6 and Sp1 expression in breast cancer patient’s sample." (PMID 31336725, 2019). "Specific suppression of TMBIM6 expression through RNA interference leads to the cell death and reduced tumor development in nasopharyngeal carcinoma, prostate carcinoma cells, and breast cancer cells." (PMID 31336725, 2019). "In addition, the correlation analysis of RNA-seq data of 422 breast cancer samples in TCGA database infers that Sp1 could activate the TMBIM6 expression." (PMID 31336725, 2019). "In breast cancer models, polypropylene increased AP2M1, PTP4A2, and TMBIM6 while reducing FTH1, a pattern consistent with enhanced trafficking/ER-stress signaling and diminished iron-mediated tumor suppressive functions." (PMID 41378310, 2025). "For breast cancer, miR-483-3p and miR-138-5p showed favorable predictions against ABCB1/PTP4A2 and TMBIM6, respectively, while miR-365 and miR-331-3p mapped to ABCG2/AP2M1." (PMID 41378310, 2025). "PKCδ supports the survival of MDA-MB-231 breast cancer cells and non-small cell lung cancer (NSCLC) cells, in which TMBIM6 expression is reportingly increased." (PMID 31336725, 2019). "Other genes affected by MPs in breast cancer include FTH1, PTP4A2, and TMBIM6." (PMID 41378310, 2025). "We also found that the gene expression of TMBIM6, AP2M1, and PTP4A2, which are correlated with cancer progression and the cell cycle, was significantly increased by PPMP incubation in MDA-MB-231 human breast cancer cells, suggesting that PPMPs regulate the transcriptional activity of cancer cells." (PMID 37069244, 2023). "Furthermore, the Kaplan Meier-plot and PrognoScan revealed that high expression of TMBIM6 was not beneficial for the prognosis of breast cancer." (PMID 37057283, 2023).
prostate carcinoma (7 papers, 2011 to 2025). A carcinoma that arises from epithelial cells of the prostate gland. "Accordingly, we performed several analyses to determine the lncRNAs associated with TMBIM6 in their role within the ceRNA network in prostate cancer." (PMID 41516091, 2025). "Here, we show that TMBIM6 is closely associated with survival in patients with cervical, breast, lung, and prostate cancer." (PMID 32782388, 2020). "Co-expression analysis identified a significant number of genes that are co-expressed with TMBIM6 in prostate cancer." (PMID 41516091, 2025). "Analysis of the TCGA-GTEx dataset also revealed increased expression of TMBIM6 in prostate cancer tissues, which is in line with these findings." (PMID 41516091, 2025). "Among them, TMBIM6 has drawn considerable attention for its involvement in the progression of a wide range of cancers, including prostate cancer." (PMID 41516091, 2025). "Considering the potential of TMBIM6 as a prognostic marker in prostate cancer, a comprehensive investigation using bioinformatics analysis is essential." (PMID 41516091, 2025). "We examined four GEO datasets (GSE29079, GSE179321, GSE17951, and GSE32571) to investigate the expression level of TMBIM6 in prostate cancer." (PMID 41516091, 2025). "TMBIM6 is known to mediate the Ca2+ pathway regulating the progression of multiple cancers, including cervical, breast, lung, and prostate cancers." (PMID 40610429, 2025). "The correlation between immune infiltration and TMBIM6 in prostate cancer is revealed by analyzing immune cell infiltration in the tumor microenvironment (TME)." (PMID 41516091, 2025). "TMBIM6 has been reported to exhibit elevated expression levels in various malignancies, including fibrosarcoma, cervical, breast, lung, nasopharyngeal, and prostate cancers." (PMID 40610429, 2025). "Significantly, specific down-regulation of TMBIM6 by RNA interference in prostate cancer cells has been reported to result in cell death." (PMID 37057283, 2023). "These analyses revealed that TMBIM6 significantly overexpressed in fibrosarcoma, cervical, endometrial and vulvar, breast, lung, and prostate cancers." (PMID 32782388, 2020). "Interestingly, in addition to its prognostic significance, our correlation analysis provides further insight into the biological role of TMBIM6 in prostate cancer." (PMID 41516091, 2025). "Previous study demonstrated that the downregulation of TMBIM6 triggers programmed cell death in prostate cancer cells, and therefore this protein might be a promising target for therapy." (PMID 41516091, 2025). "Based upon our findings and limitation of the study, research should experimentally validate the proposed DHRS4-AS1/hsa-miR-222-3p/TMBIM6 axis through in vitro binding assays, functional knockdown/overexpression studies, and in vivo prostate cancer models to confirm its mechanistic role." (PMID 41516091, 2025). "Therefore, this study aims to investigate the specific function of TMBIM6 in the progression of prostate cancer by identifying the ceRNA network, which has provided new therapeutic avenues for cancers." (PMID 41516091, 2025). "The resulting ceRNA axis, TMBIM6/has-miR222-3p/DHRS4-AS1, was identified as potential regulatory mechanism involved in prostate cancer progression." (PMID 41516091, 2025). "However, the role of TMBIM6 in the progression of prostate cancer cells has not been thoroughly explored." (PMID 41516091, 2025).
Obesity (6 papers, 2010 to 2025). Accumulation of substantial excess body fat. "We show that TMBIM6 deficiency alters glucose-dependent Ca2+ signaling in pancreatic β cells thereby instigating increased insulin secretion, a well-established direct cause for obesity and hepatic steatosis." (PMID 32394396, 2020). "TMBIM6 has been implicated with obesity and diabetes before, as it is downregulated in liver and muscle of genetically obese ob/ob and db/db mice as well as in mice with diet-induced obesity." (PMID 32394396, 2020). "The deficiency of Tmbim6 suppressed glucose metabolism and could lead to obesity." (PMID 39120858, 2024). "It was previously shown that TMBIM6 overexpression improves glucose metabolism and that TMBIM6 knockout mice develop obesity." (PMID 32394396, 2020). "To better understand the mechanism by which absence of TMBIM6 leads to obesity, we performed a comprehensive metabolic phenotyping of TMBIM6−/− mice comprising indirect calorimetry, euglycemic-hyperinsulinemic, and hyperglycemic clamp experiments." (PMID 32394396, 2020).
Hyperglycemia (3 papers, 2016 to 2024). An increased concentration of glucose in the blood. "On the other hand, overexpression of TMBIM6 by adenoviral gene transfer reversed hyperglycemia in normal mice and in diet-induced obese mice which was partially explained by an increased insulin sensitivity and reduction of hepatic glucose production." (PMID 32394396, 2020). "On the other hand, overexpression of TMBIM6 by adenoviral gene transfer dramatically improved glucose metabolism in lean and diet-induced obese mice and reversed hyperglycemia in db/db mice, which was accounted for by lower gluconeogenesis and improved insulin sensitivity." (PMID 32394396, 2020).
injury (3 papers, 2019 to 2020). Damage inflicted on the body as the direct or indirect result of an external force, with or without disruption of structural continuity. "Here, we identified Bax inhibitor 1 (BI-1), an evolutionarily conserved protein encoded by the transmembrane BAX inhibitor motif-containing 6 (TMBIM6) gene, as a novel modulator of ER-stress-induced apoptosis after HI brain injury in a neonatal rat pup." (PMID 31636086, 2019). "We explored the role of Bax Inhibitor-1 (BI-1) protein, encoded by the Transmembrane Bax inhibitor Motif Containing 6 (TMBIM6) gene, in protection from ER stress after HI brain injury." (PMID 31472686, 2019).
lung cancer (3 papers, 2020 to 2024). A malignant neoplasm involving the lung. "Given the observed upregulation of TMBIM6 in breast, prostate, cervical, and lung cancers, changes in metabolism mediated by mTORC2 and especially AKT are likely a major mechanism for cancer progression." (PMID 32782388, 2020). "Similarly, in non‐small cell lung cancer, TMBIM6 expression was found to correlate with tumor growth and metastasis, indicating its potential as a prognostic biomarker and therapeutic target." (PMID 38766879, 2024).
squamous cervical cancer (3 papers, 2016 to 2021). "TMBIM6 is overexpressed and has oncogene roles in multiple cancers such as squamous cervical cancer, non-small cell lung, breast, and nasopharyngeal cancers." (PMID 33637103, 2021). "Thus, CHCHD1, SRSF9 and TMBIM6 seem to be suitable reference genes for studying hypoxia-related gene expression in squamous cervical cancer samples by RT-qPCR." (PMID 27244197, 2016).
breast invasive carcinoma (2 papers, 2019 to 2023). "In addition, the TCGA dataset analysis was carried out to analyze the impact of high expression of Sp1 and TMBIM6 on the prognosis of breast invasive carcinoma patients." (PMID 31336725, 2019).